SPAG4 (sperm associated antigen 4)
Description:
Involved in spermatogenesis. Required for sperm head formation but not required to establish and maintain general polarity of the sperm head. Required for anchoring and organization of the manchette. Required for targeting of SUN3 and probably SYNE1 through a probable SUN1:SYNE3 LINC complex to the nuclear envelope and involved in accurate posterior sperm head localization of the complex. May anchor SUN3 the nuclear envelope. Involved in maintenance of the nuclear envelope integrity. May assist the organization and assembly of outer dense fibers (ODFs), a specific structure of the sperm tail.
Synonyms: SUN4; CT127
Tractability: Antibody: UniProt predicts a signal peptide or a membrane-spanning region. PROTAC: ubiquitination databases record sites on it.
Gene: Protein-coding gene on chromosome 20 (35,615,829 to 35,621,613, forward strand). Ensembl gene ENSG00000061656.
Subcellular location: Membrane; Cytoplasm, cytoskeleton; Cytoplasm, cytoskeleton, flagellum axoneme; Nucleus envelope; Nucleus inner membrane
Gene Ontology:
Molecular function: protein binding; structural molecule activity
Biological process: spermatogenesis
Cellular component: meiotic nuclear membrane microtubule tethering complex; nuclear envelope; nuclear inner membrane; cytoskeleton; membrane
Genetic constraint (gnomAD): Loss-of-function variants: 56 observed, 54.64 expected, observed/expected ratio (o/e) 1.02, 90% interval 0.83 to 1.28. The upper end of that interval is the gene's LOEUF score, 1.28, which puts it in group 5 of 6, group 1 being the genes least tolerant of losing a copy. Missense variants: 548 observed, 549.09 expected, observed/expected ratio (o/e) 1, 90% interval 0.93 to 1.07. Synonymous variants: 246 observed, 230.92 expected, observed/expected ratio (o/e) 1.07, 90% interval 0.96 to 1.18.
Homologues: Orthologues: chimpanzee SPAG4 (99% identical), macaque SPAG4 (97% identical), dog SPAG4 (88% identical), pig SPAG4 (87% identical), rabbit SPAG4 (86% identical), mouse Spag4 (82% identical), guinea pig SPAG4 (73% identical), rat Spag4 (68% identical), Caenorhabditis elegans unc-84 (20% identical). Paralogues in human: SUN5 (30% identical), SUN1 (27% identical), SUN2 (26% identical), SUN3 (20% identical).
Diseases named in the same sentence as SPAG4 in open-access papers:
SPAG4 is named in the same sentence as 22 diseases in open-access papers, as found by Europe PMC text mining. Sharing a sentence is not in itself a finding about the gene and the disease. The quoted sentences say what the papers report.
lung carcinoma (4 papers, 2019 to 2024). "Recent studies have highlighted the pathological role of sperm-associated antigen 4 (SPAG4) in cooperation with Nesprin-3 in lung cancer cell migration." (PMID 38566066, 2024). "The study revealed that this interaction promotes the development of lung cancer, and a reduction in the migration of lung cancer cells can be observed when nesprin-3 or SPAG4 are knocked out." (PMID 31828088, 2019). "SPAG4 could act as a potential biomarker of glioblastoma progression and prognosis, as well as in renal cell carcinoma and lung carcinoma." (PMID 35227274, 2022). "However, in recent years, SPAG4 was found greatly upregulated in a wide range of neoplastic tissues, eventually, becoming a new marker for lung cancer." (PMID 31828088, 2019).
male infertility (4 papers, 2015 to 2024). The inability of the male to effect fertilization of an ovum after a specified period of unprotected intercourse. "Furthermore, Spag4−/− mice have been reported to exhibit an irregular sperm head, damaged NE, and male infertility." (PMID 30866452, 2019). "In contrast, deficiency of SPAG4/SUN4, the second testis-specific SUN-domain protein and reported ODF1-binding protein caused disjunction of the manchette and male infertility but not decapitation." (PMID 32859975, 2020).
glioblastoma (3 papers, 2021 to 2024). The most malignant astrocytic tumor (WHO grade IV). "SPAG4 promotes survival of cancer cells under hypoxic conditions and leads to poor prognosis of several cancers, including renal cell carcinoma, glioblastoma, Pancreatic Ductal Adenocarcinoma." (PMID 33747908, 2021).
glioma (2 papers, 2021 to 2024). A benign or malignant brain and spinal cord tumor that arises from glial cells (astrocytes, oligodendrocytes, ependymal cells). "SPAG4, was also defined as a novel potential cancer marker 55, however, the level of SPAG4 expression was decreased in glioma cells treated by glutamine deprivation." (PMID 38169546, 2024). "SPAG4 is a member of the cancer testis (CT) gene family and to date, little is known about its physiological function or its involvement in tumour biology, but there is a research that it is a potential marker in glioma." (PMID 33553434, 2021).
infertile (2 papers, 2015). "According to similar phenotypes of SEPT12 in null mice and the knockout of SPAG4 in Drosophila, we suggest that the loss of SEPT12 affects the biological functionality of SPAG4 and results in teratozospermia in infertile men." (PMID 25775403, 2015).
pancreatic ductal adenocarcinoma (2 papers, 2020 to 2021). An infiltrating adenocarcinoma that arises from the epithelial cells of the pancreas. "A three-gene glycolytic signature (MET, B3GNT3 and SPAG4) can act as an independent factor for generating a prognosis for patients with pancreatic ductal adenocarcinoma." (PMID 32467671, 2020).
preeclampsia (2 papers, 2013 to 2016). Preeclampsia is a hypertensive disorder of pregnancy that is characterized by new-onset hypertension with proteinuria presenting after 20 weeks of gestation, and depending on mild or severe forms may initially present with severe headache, visual disturbances, and hyperreflexia. "Interestingly and in accordance with the role of hypoxia in preeclampsia, HIF1A can regulate the expression of several top DEGs identified in the meta-analysis including: LEP, FLT1, INHA, BHLHE40, SPAG4, HK2, HILPDA and ERO1L." (PMID 27802351, 2016). "Other genes as SPAG4, HEXB, TPI1 and QSOX1 are basically unknown in preeclampsia (and even during normal pregnancy)." (PMID 24219996, 2013).
gastric cancer (1 paper, 2026). A primary or metastatic malignant neoplasm involving the stomach. "This study reveals a novel mechanism wherein tRF-3005a promotes gastric cancer development by regulating RALY-mediated alternative splicing of SPAG4 to activate the GRB14/PI3K/AKT pathway, suggesting it may serve as a prognostic biomarker and therapeutic target." (PMID 41872130, 2026).
hepatocellular carcinoma (1 paper, 2024). A malignant tumor that arises from hepatocytes. "RNA sequencing studies indicate that SPAG4 overexpression activates the lipogenesis state and the SREBP1-mediated pathway, providing evidence for its role in lipid metabolism dysregulation and tumor progression in hepatocellular carcinoma." (PMID 39830981, 2024).
liver cancer (1 paper, 2024). An epithelial or non-epithelial malignant neoplasm that arises from the liver. "Database analysis and immunohistochemistry have revealed elevated SPAG4 levels with prognostic significance in liver cancer." (PMID 39830981, 2024).
periodontitis (1 paper, 2023). An acute or chronic inflammatory process that affects the tissues that surround and support the teeth. "The SPAG4, CCDC69, KRT10, CXCL12, HPGD, CLDN20 and CCL187 genes were the most important cross-talk genes between periodontitis and IgAN." (PMID 36793719, 2023). "By taking the intersection of WGCNA important module genes and DEGs, we found that the SPAG4, CCDC69, KRT10, CXCL12, HPGD, CLDN20 and CCL187 genes were the most important cross-talk genes between periodontitis and IgAN." (PMID 36793719, 2023). "By taking the intersection of WGCNA important module genes and DEGs, we found that the SPAG4, CCDC69, KRT10, CXCL12, HPGD, CLDN20 and CCL187 genes were the most important cross-talk genes between periodontitis and IgAN, and these genes may be related to kinase regulator activity." (PMID 36793719, 2023).
renal clear cell carcinoma (1 paper, 2024). "Furthermore, SPAG4 upregulation in renal clear cell carcinoma (RCC), regulated by hypoxia via HIF-1 and VHL, has been shown to enhance tumor cell migration and invasion, while SPAG4 knockdown reduces RCC cell invasiveness in vitro." (PMID 39830981, 2024).
systemic lupus erythematosus (1 paper, 2024). An autoimmune multi-organ disease typically associated with vasculopathy and autoantibody production. "Additionally, SPAG4 was predominantly linked to the systemic lupus erythematosus disease-related pathway." (PMID 39830981, 2024).
testicular cancer (1 paper, 2019). A primary or metastatic malignant neoplasm that affects the testis. "Second, SEPT12 expression altered the nuclear membrane localization of SPAG4, as observed through confocal microscopy, in a human testicular cancer cell line." (PMID 30866452, 2019).
testicular embryonal carcinoma (1 paper, 2019). A malignant germ cell neoplasm arising from the testis. "Because SEPT12 and SPAG4 are testis-specific proteins, we selected NT2/D1, a pluripotent human testicular embryonal carcinoma cell line, to evaluate the effects of SEPT12 on SPAG4/LAMINB complexes." (PMID 30866452, 2019).
tumor (12 papers, 2020 to 2025). "In the developed OS prognostic model, differential gene expression analysis showed a higher expression of SPAG4 in the high-risk group, supporting the hypothesis that SPAG4 acts as a tumor promoter in OS." (PMID 35095893, 2021). "Inhibition of this pathway by LY294002 effectively neutralized the tumor‐promoting effects of SPAG4, highlighting its potential as a therapeutic target in CRC metabolic reprogramming." (PMID 40740483, 2025). "SIK1, a serine/threonine kinase, regulates the cell cycle and gluconeogenesis and acts as a tumor suppressor; SPAG4 and JUNB regulate cell proliferation and differentiation." (PMID 39025980, 2024). "Our in vivo investigations using a subcutaneous xenograft model have confirmed SPAG4’s influence on tumor growth and its capacity to modulate the immune microenvironment." (PMID 39539547, 2024). "AP2S1, P3H4 (SC65), SPAG4, PLA2G2F, PTPN6, RAC3, and ETV7 were identified as candidate tumor-associated antigens." (PMID 35814377, 2022). "A previous study reported tumor-specific markers (RHCG and LINC01187) of chRCC through bulk RNA sequencing data from TCGA, similar results and new tumor-specific markers (SPAG4) were achieved in the present study using scRNA-seq." (PMID 34722263, 2021). "Recently, SPAG4 knockdown has been shown to reduce the invasion and migration abilities of cancer cells, while its overexpression enhanced these abilities of tumor cells." (PMID 35095893, 2021). "The expression levels of ZBTB32 and DEPTOR were higher in normal tissues than in tumor tissues (P <0.001), while the opposite was true for SPAG4 expression (P <0.001)." (PMID 35095893, 2021). "Notably, a substantial reduction in tumor volume was observed 28 days post-treatment with sh-SPAG4 compared to the sh-GFP group." (PMID 39539547, 2024). "In addition, a novel tumor-specific gene marker called SPAG4 was discovered in chRCC and it was more specifically expressed in chRCC3." (PMID 34722263, 2021). "In the present study, we found that the expression of SPAG4 was higher in patients with OS, suggesting that this gene might act as a tumor promoter." (PMID 35095893, 2021). "In tumor tissues, SPAG4 was overexpressed while ZBTB32 and DEPTOR were downregulated." (PMID 35095893, 2021). "Some new tumor-specific markers for different pathologic types of RCC, such as SPOCK1, PTGIS, REG1A, CP and SPAG4 were identified and validated." (PMID 34722263, 2021). "We identified six TAA protHLAIp that were exclusively detected in the tumor tissue of C3N-02289 (BIRC5, TERT, FAP, SPAG4, MAGEA9, and BCL2L1)." (PMID 32157095, 2020). "Thus, the results identified some new tumor-specific markers and verified SPOCK1, PTGIS, REG1A, CP and SPAG4 in different types of RCC." (PMID 34722263, 2021). "Molecular factors such as PTPRH, CPNE1, APLN, PLOD1, SPAG4, B7‐H3, and SIK2 have been shown to facilitate carcinogenesis and glycolysis via PI3K/AKT induction, whereas inhibitors of this pathway reduce glycolytic flux, diminish tumor growth, and increase sensitivity to anticancer drugs." (PMID 40740483, 2025).
cancer (7 papers, 2020 to 2024). A tumor composed of atypical neoplastic, often pleomorphic cells that invade other tissues. "SPAG4, a protein associated with sperm function, has recently been implicated in the regulation of Reactive Oxygen Species (ROS) in the context of cancer cell biology." (PMID 39539547, 2024). "Although this function of SPAG4 has been shown in other cancers, only few studies have investigated the role of SPAG4 in OS cells; therefore, further studies are necessary to confirm these findings." (PMID 35095893, 2021). "The results of RT-PCR indicated that GPC1, STC2, P4HA4, and ENO3 were upregulated in cancer cells while SPAG4 was downregulated in the five cancer cells." (PMID 33747908, 2021). "SPAG4 has been reported as a clinically relevant cancer marker." (PMID 35095893, 2021).
SPAG4 also shares sentences with these, for which no sentence is quoted: Globozoospermia (3 papers); renal cell carcinoma (2); diabetes (1); osteosarcoma (1); type 2 diabetes (1).